NTRK3 (neurotrophic receptor tyrosine kinase 3)
Diseases named in the same sentence as NTRK3 in open-access papers (continued):
Sharing a sentence is not in itself a finding about the gene and the disease.
NTRK3 also shares sentences with these, for which no sentence is quoted: acute myeloid leukemia (8 papers); leukemia (7); gastrointestinal stromal tumor (6); head and neck squamous cell carcinoma (6); prostate carcinoma (6); infection (5); amyotrophic lateral sclerosis (4); dermatofibrosarcoma protuberans (4); inflammatory myofibroblastic tumor (4); salivary duct carcinoma (4); glaucoma (3); neurodegenerative disease (3); non-small cell lung carcinoma (3); pancreatic adenocarcinoma (3); pilocytic astrocytoma (3); solitary fibrous tumor (3); alcohol dependence (2); angiomatoid fibrous histiocytoma (2); Asperger syndrome (2); bipolar disorder (2); bone sarcoma (2); cervical sarcoma (2); cholangiocarcinoma (2); clear cell carcinoma (2); colon adenoma (2); cutaneous melanoma (2); cylindroma (2); ductal carcinoma (2); ductal carcinoma in situ (2); endometrial cancer (2).
A further 126 diseases each share a sentence with NTRK3 in 2 papers or fewer.